SHBG (sex hormone binding globulin)
Diseases named in the same sentence as SHBG in open-access papers (continued):
Sharing a sentence is not in itself a finding about the gene and the disease.
type 2 diabetes (continued). "However, the exact biological mechanism by which serum SHBG influences type 2 diabetes is poorly understood, and experimental studies into the mechanism of action are scarce and sometimes contradictory." (PMID 36114428, 2023). "However, it remains to be elucidated to what extent serum SHBG mediates the association between IHL accumulation and type 2 diabetes." (PMID 36114428, 2023). "Serum SHBG significantly mediated the association between IHL content and type 2 diabetes." (PMID 36114428, 2023). "Indeed, the indirect effects of our mediation analyses suggest that a single percentage point increase in IHL content is associated with 8–12% higher odds of type 2 diabetes overall and 2–4% higher odds of type 2 diabetes when mediated via serum SHBG." (PMID 36114428, 2023). "Even more recently, SHBG has been identified as a hepatokine that protects from type 2 diabetes." (PMID 35132570, 2022). "Surprisingly, epidemiological studies showed that not low but high serum SHBG was associated with increased all-cause mortality in men with type 2 diabetes and was connected with the increased risk of cardiovascular diseases." (PMID 32326011, 2020). "Sex hormones such as sex hormone-binding globulin have been identified to have sex-dependent effects on leptin and Type 2 diabetes, and might explain the sex-dependent effects of leptin that were observed in this study." (PMID 32374776, 2020). "There was little evidence for an association of genetic liability to type 2 diabetes, parity, or circulating levels of 25-hydroxyvitamin D and sex hormone binding globulin with ovarian cancer or its subtypes." (PMID 31390370, 2019). "Therefore, reduction in the sex hormone binding globulin (SHBG) and high levels of free testosterone are accepted for the occurrence of diabetes type 2 and highlights the relationship between androgens and insulin sensitivity." (PMID 30647752, 2018). "Circulating SHBG concentrations correlate positively with insulin sensitivity in humans, suggesting that circulating SHBG might prevent the development of type 2 diabetes." (PMID 30374329, 2018). "We conducted this cross-sectional study to delineate whether MS or NAFLD has more impact on circulating SHBG levels in type 2 diabetes (T2D) patients." (PMID 29109457, 2017). "Because fatty liver is a strong risk factor of type 2 diabetes, investigating whether fatty liver accounts for the SHBG and type 2 diabetes relation may provide further insight into the role of SHBG in the pathogenesis of type 2 diabetes." (PMID 23066943, 2012). "Moreover, the previous studies examining the relation between SHBG and type 2 diabetes are mainly from European populations." (PMID 23066943, 2012). "Type II diabetes is related to hyperinsulinaemia, which may increase free oestrogen levels by decreasing the concentration of sex hormone-binding globulin." (PMID 17912243, 2007). "A closer examination of the PRST2D × SHBG interaction in women showed that having both high SHBG and high PRST2D risk confers higher odds of developing type 2 diabetes than would be expected from additive or multiplicative effects and that an interaction may indeed be present." (PMID 40892850, 2025). "However, it remains uncertain whether serum SHBG mediates the association between intrahepatic lipids (IHL) and type 2 diabetes." (PMID 36114428, 2023). "Therefore, the aim of the present study was to assess whether, and to what extent, serum SHBG has a mediating role in the association between IHL content and type 2 diabetes in a population-based cohort." (PMID 36114428, 2023). "Therefore, we studied whether, and to what extent, serum SHBG mediates the association between IHL content and type 2 diabetes." (PMID 36114428, 2023).
type 2 diabetes (continued). "SHBG is of interest in biomarker research for its association at low levels with type-II diabetes and metabolic syndrome but, although elevated SHBG is seen following weight loss, this glycoprotein has not previously been considered as a prognostic marker of growth faltering." (PMID 31730639, 2019). "In the current study, we showed that neither SHBG levels nor androgen levels (both of which might be associated with menopause and with type 2 diabetes) could explain the association between early onset of natural menopause and risk of type 2 diabetes." (PMID 28721436, 2017). "Furthermore, participants with type 2 diabetes had a higher median IHL content and lower serum SHBG levels." (PMID 36114428, 2023). "Multivariable MR analysis results suggested that sex hormone-binding globulin attenuated the effect of fitness on type 2 diabetes but not completely." (PMID 37400433, 2023). "We conclude that the beneficial effects of red wine on the metabolic syndrome and it associated co-morbidities, including cardiovascular disease and type 2 diabetes, may be mediated in part by resveratrol acting via CAR to increase plasma SHBG levels." (PMID 28947831, 2017). "Nevertheless, in some analyses, there was a considerable uncertainty in the estimated proportion mediated, particularly when the direct effect (i.e. the effect of IHL content on type 2 diabetes that was not attributable to serum SHBG) was not statistically significant." (PMID 36114428, 2023). "Interestingly, MRA has revealed that obesity, testosterone and SHBG play a causal role in PCOS, but PCOS had no direct causal effect on type 2 diabetes or CVD." (PMID 36897358, 2023). "Finally, levels of FSH and SHBG were 35 and 43 % lower in obese men, respectively, irrespective of type 2 diabetes, whereas LH levels were similar among the groups." (PMID 25771885, 2015). "However, recent studies showed that low SHBG can predict the future development of type 2 diabetes, independent of the testosterone concentration." (PMID 24069277, 2013). "Low SHBG concentrations have been shown to predict the development of type 2 diabetes, independent of glucose and insulin, in premenopausal women and may play a role in its pathogenesis." (PMID 23936766, 2013).
metabolic syndrome (141 papers, 2008 to 2025). A cluster of metabolic risk factors for CARDIOVASCULAR DISEASES and TYPE 2 DIABETES MELLITUS. "The strength of this study is that it is the first to comprehensively compare the associations of dyslipidemia with SHBG, E2, TT, and DHEAS." (PMID 40495241, 2025). "Because of the significant correlation between SHBG and metabolic disorders, decreased levels of SHBG as a laboratory marker of increased risk of metabolic syndrome (MS) are being discussed, especially in the male population." (PMID 40427034, 2025). "The association between SHBG levels and the presence of dyslipidemia was investigated in comparison with other sex hormones." (PMID 40495241, 2025). "In this study, we aim to collect and summarize current knowledge about the physiology of SHBG and its association with cardiovascular disease, metabolic syndrome, DM 2, thyroid function, PCOS, and infertility." (PMID 40427034, 2025). "The multivariate analysis revealed that SHBG levels were significantly associated with dyslipidemia." (PMID 40495241, 2025). "In Model 1, SHBG levels were significantly associated with the presence of dyslipidemia (ORs: 0.757, 95% CIs: [0.610–0.934], P = 0.010), whereas in Model 2, this association was not significant (ORs: 0.786, 95% CIs: [0.591–1.036], P = 0.092)." (PMID 40495241, 2025). "Our findings were also supported by previous data showing that increased circulating SHBG levels were linked to lower risks of metabolic syndrome and cardiovascular events, thus reducing the risk of stroke." (PMID 40728963, 2025). "In conclusion, among postmenopausal women, SHBG levels were most strongly associated with dyslipidemia among E2, TT, and DHEAS levels." (PMID 40495241, 2025). "SHBG levels were significantly associated with dyslipidemia in postmenopausal women and outperformed E2, TT, and DHEAS levels." (PMID 40495241, 2025). "In this study, the association between SHBG and dyslipidemia differed from that observed in the case of E2 and TT." (PMID 40495241, 2025). "SHBG is a glycoprotein that not only controls serum sex hormone levels but is also strongly correlated with metabolic syndrome, cardiovascular risk, thyroid function, gynecological conditions, and even the process of carcinogenesis." (PMID 40427034, 2025). "Multivariate logistic regression analysis in Model 2 demonstrated a significant association between SHBG levels and the presence of dyslipidemia (OR: 0.745, 95% CI: [0.576–0.958], P = 0.022)." (PMID 40495241, 2025). "The present study evaluated the association between SHBG and metabolic syndrome among middle-aged and elderly males in china." (PMID 38988998, 2024). "Risk of incident metabolic syndrome with each quartile decrease of SHBG levels in different subgroups at follow up." (PMID 38988998, 2024). "Reduced levels of testosterone and SHBG are both associated with metabolic syndrome and fatty liver." (PMID 39768643, 2024). "A study on elderly prediabetic and elderly male populations in China found that lower levels of sex hormone-binding globulin (SHBG) were independently associated with metabolic syndrome." (PMID 37964953, 2023). "The circulating concentration of SHBG is associated with glucose metabolism, adiposity, and components of the metabolic syndrome; therefore, liver disease can affect the plasma proteome." (PMID 35565913, 2022). "Low serum SHBG concentrations are associated with metabolic syndrome, T2DM and increased risk for cardiovascular problems." (PMID 34441954, 2021). "SHBG was significantly associated with IR and atherogenic dyslipidemia, while FAI levels were linked to hypertension, independently of other factors considered." (PMID 34089497, 2021). "It is also well established that low plasma SHBG levels are present in subjects suffering the metabolic syndrome and predict a higher risk of suffering cardiovascular disease." (PMID 28947831, 2017).
metabolic syndrome (continued). "Low plasma SHBG levels are associated with obesity and the metabolic syndrome predicting risk for type 2 diabetes and cardiovascular disease." (PMID 28947831, 2017). "The combination of low 25(OH)D and low SHBG was still associated with the highest odds of metabolic syndrome." (PMID 26825918, 2016). "This study assessed the association between SHBG, sex hormones and prevalence of metabolic syndrome." (PMID 24714992, 2014). "We conclude that low serum levels of SHBG were associated with higher prevalence of metabolic syndrome in our sample of adult Brazilian males aged 40-70 years." (PMID 24714992, 2014). "Additional prospective studies to assess this association directly are required, especially with regard to the potential causal relationship between SHBG and metabolic syndrome." (PMID 24714992, 2014). "Low serum levels of SHBG are associated with higher prevalence of metabolic syndrome among male patients, but further studies are required to confirm this association." (PMID 24714992, 2014). "The current study was not intended to evaluate potential causal relationships between SHBG and metabolic syndrome." (PMID 24714992, 2014). "The objective here was to evaluate the association between sex hormone-binding globulin (SHBG), sex hormones and metabolic syndrome among men." (PMID 24714992, 2014). "The association between low testosterone/low SHBG levels and the metabolic syndrome is beyond any reasonable doubt now." (PMID 18266714, 2008). "Similarly, in Model 1, SHBG levels were significantly associated with dyslipidemia, aligning with the findings in Model 2 (OR: 0.728, 95% CI: [0.598–0.884], P = 0.001)." (PMID 40495241, 2025). "Although the association between E2 and SHBG levels and dyslipidemia in postmenopausal women has been consistently reported, the relationship between testosterone and dyslipidemia in these women remains unclear because evidence both supports and opposes." (PMID 40495241, 2025). "This study hypothesized that SHBG would show the strongest association with dyslipidemia among postmenopausal women, relative to other circulating sex hormones." (PMID 40495241, 2025). "Although an association between SHBG levels and dyslipidemia in postmenopausal women has been previously reported, it remains unclear whether SHBG levels are more strongly associated with dyslipidemia than the other sex hormones." (PMID 40495241, 2025). "In this review, we aim to gather and summarize current knowledge on the physiology of SHBG and its association with cardiovascular disease, metabolic syndrome, DM 2, thyroid function, PCOS, hypogonadism, infertility, and its correlations with oral contraception." (PMID 40427034, 2025). "In addition, an exploratory analysis was conducted to examine the association between SHBG quartiles and dyslipidemia risk." (PMID 40495241, 2025). "SHBG, a hepatic glycoprotein that transports testosterone and other steroids in the circulation, has emerged as a promising biomarker for assessing MetS risk due to its strong associations with key metabolic indicators such as IR, adiposity, and dyslipidemia." (PMID 40863113, 2025). "These functions could be pivotal in the protective capacity of SHBG, contributing to its ability to lower the risk of metabolic syndrome." (PMID 39055720, 2024). "SHBG also possesses anti-inflammatory and lipolytic effects on adipocytes and macrophages, which may account for its link to reduced incidence rates of metabolic syndrome and its associated complications." (PMID 39768643, 2024). "SHBG concentrations are associated with keyfeatures of metabolic syndrome in these women." (PMID 39411775, 2024). "Circulating SHBG levels are strongly associated with metabolic and hormonal factors, and their systemic level has been found to be decreased in patients with obesity, type second diabetes, or metabolic syndrome." (PMID 38874666, 2024).
metabolic syndrome (continued). "Deficiency in thyroid hormones can also be associated with weight gain and excess body mass, dyslipidemia, decreased sex hormone-binding globulin (SHBG) levels, and increased conversion of androstenedione to testosterone; these disturbances are also observed in women with PCOS." (PMID 36673125, 2023). "We previously showed that a low circulating SHBG level (<30 nmol/L) is associated with the presence of the metabolic syndrome in a multiethnic population with lower levels found in both men and women of Pakistan ethnic origin compared with Caucasian and African-Caribbean origin people." (PMID 34386722, 2021). "We evaluated the association of SHBG with BMI among the 693 prepubertal children subdivided into normal, overweight, and obese groups, with plasma lipid levels among the children subdivided into normal and dyslipidemia groups." (PMID 33291623, 2020). "Furthermore, the lower serum SHBG levels with metabolic syndrome have been identified as a risk of PCOS in adolescents." (PMID 33139661, 2020). "Hyperandrogenic states and aspects of metabolic syndrome are both commonly associated with lower SHBG levels, which may help explain lower SHBG in PCOS." (PMID 31870342, 2019). "In conclusion, SHBG suppresses inflammation and lipid accumulation in macrophages and adipocytes, which might be among the mechanisms underlying the protective effect of SHBG, that is, its actions which reduce the incidence of metabolic syndrome." (PMID 30046278, 2018). "We further explored the association of SHBG and 25(OH)D in combination with metabolic syndrome." (PMID 26825918, 2016). "In addition, men who present low SHBG concentrations are at increased risk of developing metabolic syndrome." (PMID 24714992, 2014). "Furthermore, previous studies had also showed that the levels of total testosterone and SHBG were negatively associated with metabolic syndrome while the levels of serum ferritin was in a positive association with metabolic syndrome." (PMID 24146788, 2013). "Therefore, serum SHBG concentration may be an independent and significant risk factor for metabolic syndrome." (PMID 38988998, 2024). "Furthermore, SHBG has anti-inflammatory and lipolytic effects on adipocytes and macrophages, which could explain its association with lower incidence rates of metabolic syndrome and its complications." (PMID 36482993, 2022). "In conclusion, at a physiological concentration, SHBG suppresses inflammation and lipid accumulation in macrophages and adipocytes, which may be among the mechanisms underlying the protective effect of SHBG which acts to suppress the development of metabolic syndrome." (PMID 30046278, 2018). "Several studies have often reported low testosterone and SHBG to be associated with type 2 DM and the metabolic syndrome (MetS)." (PMID 30057912, 2018). "Thus, our discovery that resveratrol induced increases in plasma SHBG may represent a paradigm for therapeutic interventions that could reduce risk for many of the diseases associated with metabolic syndrome." (PMID 28947831, 2017). "Although this is counterintuitive because the use of potent synthetic PPARγ ligands such as insulin sensitizers, like pioglitazone, cause modest increases in plasma SHBG levels in individuals with the metabolic syndrome, the effects of these potent drugs may be multifactorial." (PMID 27113851, 2016). "Thus, the low plasma levels of adiponectin that are typically seen in overweight individuals at risk of having the metabolic syndrome may further contribute to the low plasma SHBG levels in obese patients." (PMID 27113851, 2016). "Low total testosterone (TT) and sex hormone-binding globulin (SHBG) concentrations have been associated with the metabolic syndrome (MetS) in men, but the reported strength of association varies considerably." (PMID 25019163, 2014). "The optimal cutoff value for SHBG levels in identifying dyslipidemia was determined to be 69.0 nmol/L." (PMID 40495241, 2025).